SEMA3B-AS1 (SEMA3B antisense RNA 1)
Gene: Long non-coding RNA gene on chromosome 3 (50,265,974 to 50,276,052, reverse strand). Ensembl gene ENSG00000232352.
Diseases named in the same sentence as SEMA3B-AS1 in open-access papers:
SEMA3B-AS1 is named in the same sentence as 3 diseases in open-access papers, as found by Europe PMC text mining. Sharing a sentence is not in itself a finding about the gene and the disease. The quoted sentences say what the papers report.
gastric cancer (1 paper, 2022). A primary or metastatic malignant neoplasm involving the stomach. "LncRNA SEMA3B antisense RNA 1 (head to head) (SEMA3B-AS1) has recently been shown to suppress gastric cancer." (PMID 35287551, 2022). "Long non-coding RNA (lncRNA) SEMA3B antisense RNA 1 (head to head) (SEMA3B-AS1) is a recently identified tumor suppressor in gastric cancer." (PMID 35287551, 2022).
carcinoma (1 paper, 2023). A malignant tumor arising from epithelial cells. "LncRNA Semaphorin 3B (SEMA3B) antisense RNA 1 (SEMA3B‐AS1) has been found to be dysregulated in a few carcinomas recently." (PMID 37701532, 2023).
SEMA3B-AS1 also shares sentences with these, for which no sentence is quoted: tumor (1 paper).